ING4 (inhibitor of growth family member 4)
Diseases named in the same sentence as ING4 in open-access papers (continued):
Sharing a sentence is not in itself a finding about the gene and the disease.
breast carcinoma (continued). "As the homologous of ING4, ING3 might also be related to endocrine therapy of breast cancer." (PMID 33469513, 2020). "However, ING4 overexpressing cells contained measurably less p-p65/RelA (Ser536) in both cytosolic and nuclear fractions (2- to 5-fold), indicating that phosphorylation of p65/RelA at the amino acid residue serine 536 was inhibited by ING4 overexpression in T47D and MCF7 breast cancer cells." (PMID 23056468, 2012). "Although there is no related report of ING3 in breast cancer at this stage, ING4 and ING5, as members of the ING family, participate in the occurrence of breast cancer." (PMID 33469513, 2020). "However, we found the association between low ING4 expression and high levels of p-p65/RelA in all tumors regardless of the HER2 status, suggesting that ING4 down-regulation may represent a mechanism of NF-κB activation independent of HER2/neu receptor signaling in breast cancer." (PMID 23056468, 2012).
glioma (13 papers, 2011 to 2025). A benign or malignant brain and spinal cord tumor that arises from glial cells (astrocytes, oligodendrocytes, ependymal cells). "Low ING4 expression has been associated with high-grade tumors and poor prognosis in other cancers including glioma, melanoma, and hepatocellular carcinoma." (PMID 23056468, 2012). "For instance, miR-423-5p functions as an oncogene by directly targeting the 3′-UTR of ING4, thereby suppressing its expression and promoting glioma progression." (PMID 40001584, 2025). "ING4, although expressed at lower levels in gliomas, plays a similar suppressive role in glioma progression." (PMID 40001584, 2025). "Several groups have demonstrated the interactions between ING4 and the NF-κB signaling pathway to suppress angiogenesis in glioma, colorectal and breast cancers." (PMID 36077605, 2022). "The physical interaction between ING4 and the NF-κB subunit was also observed in a glioma cell line." (PMID 36077605, 2022). "Overexpression of miR-423-5p induces upregulation of p-ERK1/2 and p-AKT, and enhances glioma cell proliferation, as well as angiogenesis and metastasis, by targeting inhibitor of growth 4 (ING-4)." (PMID 35008806, 2021). "Ectopic miR‐423‐5p highly expression in gliomas is a potential tumor promoter, targets ING‐4 expression, enhances the formation of glioblastoma neurospheres and confers resistance to temozolomide in glioma cells." (PMID 33174687, 2020). "For example, coimmunoprecipitation experiments in a glioma cell line indicated a physical interaction to occur between ING4 and RelA, the large subunit of NF-κB." (PMID 31752342, 2019). "In glioma and melanoma cancer models, however, ING4 repressed several NF-κB-target genes, thereby attenuating tumor angiogenesis and growth." (PMID 23056468, 2012). "ING4 dysregulation correlates with pathophysiological process of many tumors, such as astrocytomas, clear-cell renal carcinoma, glioblastoma, glioma and hepatocellular carcinoma." (PMID 36077605, 2022). "ING4 inhibits tumour proliferation and angiogenesis in human glioma." (PMID 35075768, 2022). "In addition, overexpression of miR‐423‐5p downregulates ING‐4 expression in glioma tissues to enhance angiogenesis and promote glioma cell invasion." (PMID 33174687, 2020). "Finally, by analyzing the relationship of protein levels amongst Bax, Bcl-2, Beclin-1, and the caspase family proteins, it was confirmed that long-term treatment with ING4 can induce parallel pathways of both autophagy and apoptotic cell death in glioma cells." (PMID 30643005, 2019). "It is believed, based on knockdown and overexpression experiments in gliomas, that ING4 interacts with the NF-κB complex by binding to RelA, leading to the downregulation of NF-κB target genes, which reinforces the idea that ING4 shows characteristics of a tumor suppressor." (PMID 31752342, 2019). "Moreover, curcumin induces G2/M phase arresting in glioma cell via upregulation of p21 and ING4, and further induces apoptosis through up-regulating BAX and down-regulating the Bcl-2 and NF-κB signaling pathway in glioma cells." (PMID 28671583, 2017). "However, so far, only ING4 was reported to play a role in glioma tumour angiogenesis and growth." (PMID 31332862, 2019). "In an in vivo glioma-bearing mice model the intravenous administration of the nanoparticles increased the median survival time and enhanced the BBB-crossing and glioma-targeting efficacy of ING4, decreasing the tumor volume." (PMID 37273792, 2023).
melanoma (12 papers, 2009 to 2025). A malignant, usually aggressive tumor composed of atypical, neoplastic melanocytes. "Reduced ING4 expression in melanoma compared to normal nevi is associated with enhanced melanoma cell proliferation." (PMID 39329914, 2024). "In glioblastoma cells and melanoma-associated endothelial cells, ING4 was shown to repress expression of several NF-κB-target genes." (PMID 23056468, 2012). "In particular, it has been proposed that the reduction of ING4 expression in head and neck squamous cell carcinoma as well as in glioblastoma and melanoma patients maybe attributed to mutations or deletions at chromosome 12p12-13, which includes Ing4 gene." (PMID 19250543, 2009). "Meanwhile, miR-650 facilitated melanoma metastasis by targeting the inhibitor of growth family member 4 (ING4)." (PMID 40861221, 2025). "The overexpression of ING4 can inhibit melanoma growth and induce apoptosis through the mitochondrial pathway by increasing Fas expression, which activates caspase-8." (PMID 39329914, 2024). "ING4 is mainly suppressed in various tumors and coming along with poor prognosis in melanoma, hepatocellular, gastric and breast tumors." (PMID 32103108, 2020). "Based on changes in expression, a six-biomarker system (composed of ING4 and five additional biomarkers) provides a more accurate prognosis for melanoma patients than any single biomarker." (PMID 30643005, 2019). "In a clinical trial, the BRMS1 drug inhibited metastasis by suppressing NF-kB activity and IL-6 expression, while inducing the expression of ING4, pointing to its possible role as a tumor suppressor in melanomas." (PMID 31752342, 2019). "In one trial, BRMS1, a metastasis suppressor, inhibited melanoma angiogenesis by suppressing NF-kB activity and IL-6 expression via induction of ING4." (PMID 30643005, 2019). "ING4 also initiates apoptosis in human melanoma A375 cells, which subsequently employs a classic extrinsic apoptotic pathway, the Fas/FasL-mediated signaling cascade." (PMID 30643005, 2019). "Increased levels of Fas, cleaved caspase-8, and caspase-3, and decreased levels of FasL and procyclic acidic repetitive protein are all observed in melanoma, demonstrating that ING4 achieves functionality via the Fas/Caspase-8 pathway." (PMID 30643005, 2019). "The differential expressions of Bim, BRG1, Cul1 and ING4 between melanoma and dysplastic nevi were confirmed by the multiple logistic regressions (p < 0.05)." (PMID 23028750, 2012). "Our previous studies found that 12 markers including pAkt, Bim, BRG1, BRMS1, CTHRC1, Cul1, ING4, MCL1, NQO1, SKP2, SNF5 and SOX4 were associated with melanoma progression." (PMID 23028750, 2012). "Four (Bim, BRG1, Cul1 and ING4) of 12 markers were significantly differentially expressed in melanoma compared with dysplastic nevi by both univariate and multiple logistic regression analysis (p < 0.01)." (PMID 23028750, 2012). "ING4 and Cul1 had the most significantly statistical differences between dysplastic nevi and melanoma." (PMID 23028750, 2012). "The results demonstrated that the expression of Bim, BRG1, Cul1 and ING4 differed significantly between melanoma and dysplastic nevi, using the optimal scale partitioning of negative, weak to moderate and strong staining of these markers." (PMID 23028750, 2012). "There was perfect separation of the 3 distributions of top-to-bottom difference scores between dysplastic nevi and melanomas, 8 of 155 melanomas lost ING4 expression, whereas 22 of 33 dysplastic nevi had strong expression." (PMID 23028750, 2012). "We found that Bim, BRG1, Cul1 and ING4 were differently expressed between melanoma and dysplastic nevi using the univariate logistic regression (p < 0.01)." (PMID 23028750, 2012). "ING4 is widely expressed in normal cell lines while it is down-regulated in glioblastoma and melanoma cells as well as in head and neck squamous cell carcinoma." (PMID 19250543, 2009).
melanoma (continued). "In conclusion, ING4 may play an anti-tumor role in melanomas through the Fas/caspase-8 apoptosis pathway, including inhibiting melanoma cell proliferation and growth and inducing apoptosis." (PMID 39329914, 2024). "ING4 expression is also considered to be a significant biomarker that may be used to discriminate melanoma from dysplastic nevi." (PMID 30643005, 2019). "Other studies have identified ING4 expression as a significant biomarker in melanoma." (PMID 31752342, 2019). "ING4 can regulate endothelial cell growth and tube formation by activating the promoter of the gene encoding JWA, a protein previously reported to inhibit melanoma cell metastasis." (PMID 30643005, 2019). "In summary, we describe a multi-marker immunohistochemical panel of Bim, BRG1, Cul1 and ING4 which may aid in differential diagnosis for melanoma from dysplastic nevi." (PMID 23028750, 2012). "-ING4 may play an anti-tumor role in melanomas through the Fas/caspase-8 apoptosis pathway." (PMID 39329914, 2024). "Overexpression of ING4 suppresses cell migration and invasion and significantly reduces the activity of matrix metalloproteinase (MMP)-2 and MMP-9 in melanoma, lung carcinoma, osteosarcoma, and astrocytoma." (PMID 30643005, 2019). "ING4 inhibited invasion and migration in a melanoma cell model in vitro while ING1 and ING4 were reported to inhibit angiogenesis in glioblastoma and to negatively correlate with microvessel density in ovarian cancers." (PMID 24962136, 2014). "Immunohistochemical expressions of 12 promising biomarkers (pAkt, Bim, BRG1, BRMS1, CTHRC1, Cul1, ING4, MCL1, NQO1, SKP2, SNF5 and SOX4) were studied in 122 melanomas and 33 dysplastic nevi on tissue microarrays." (PMID 23028750, 2012). "In our study, we found that ING4 significantly reduced the mRNA and protein expressions of MMP-2 and COX-2, which was consistent with the findings in melanoma, osteosarcoma and brain cancer, and the expression of nuclear Sp1 and subsequent DNA binding activity." (PMID 27806345, 2016). "A panel consisted of 4 markers (ING4-Cul1-BRG1-Bim) achieved 94.3% sensitivity and attained 81.8% specificity for discrimination of melanoma from dysplastic nevi, and AUC is 84.3%, higher than 71.9% for 2-markers (ING4-Cul1) and 76.9% for 3-markers (ING4-Cul1-BRG1)." (PMID 23028750, 2012). "The multiple biomarkers ING4, Cul1, BRG1 and Bim described here can aid in the discrimination of melanoma from dysplastic nevi and provide a new insight to help clinicians recognize melanoma." (PMID 23028750, 2012).
gastric cancer (7 papers, 2012 to 2023). A primary or metastatic malignant neoplasm involving the stomach. "constructed a recombinant Ad coexpressing ING4 as well as PTEN (AdVING4/PTEN) for the treatment of gastric carcinoma." (PMID 37663132, 2023). "Ad-ING4 reverses gastric cancer MDR in vitro and in vivo via the down-regulation of ATP-binding cassette transporters and activation of apoptotic pathways." (PMID 30643005, 2019). "ING4 mRNAs and protein in human gastric carcinoma tissues and cells were significantly lower compared to cells from normal tissue." (PMID 28350359, 2017). "The targets of miR-650 were predicted through at least three databases (Pictarget, miRBas and TargetScan), and ING4 was selected as a putative target, which was also recently reported in gastric cancer." (PMID 23991130, 2013). "The downregulation of ING4 has been found in many human cancers including gastric cancer, ovarian carcinoma, head and neck squamous cell carcinoma and lung cancer." (PMID 23991130, 2013). "Overexpression of ING4 resulted in the down-regulation of RelA, p-IκBα, MMP-9 and uPA proteins and inhibited proliferation and invasion in gastric carcinoma cell lines MKN-28, SGC-7901 and MKN-45." (PMID 28350359, 2017). "Therefore, combining ING4 and PTEN for gene therapy may represent an effective approach for treating human gastric carcinoma and others related tumors." (PMID 37663132, 2023).
glioblastoma (7 papers, 2009 to 2022). The most malignant astrocytic tumor (WHO grade IV). "Moreover, ING4 binds to nuclear factor NFκB p65 subunit (encoded by the RelA gene), targeting it for ubiquitinylation and proteasomal destruction, meaning that ING4 deficiency can unleash NFκB activation and favor angiogenesis in glioblastoma." (PMID 29163768, 2017). "Similarly, miR‐423‐5p targets inhibition of ING‐4 to inhibit apoptosis of glioblastoma cells." (PMID 33174687, 2020).
hepatocellular carcinoma (7 papers, 2012 to 2023). A malignant tumor that arises from hepatocytes. "ING4 was reported to negatively regulate cell proliferation (hepatocellular carcinoma) through the NF-κB/miR-155 pathway, upregulation of nuclear levels of FOXO3a and its enhanced transcriptional activity." (PMID 34685579, 2021). "ING4 overexpression in both in vivo and in vitro experiments significantly reduced hepatocellular carcinoma cell growth through cell cycle G1 phase arrest and apoptosis, inhibition of migration, and invasion." (PMID 34685579, 2021). "ING3 is downregulated in head and neck carcinoma, melanoma, and hepatocellular carcinoma, while ING4 is reduced in bladder and colorectal cancer." (PMID 34685579, 2021).
lung carcinoma (7 papers, 2012 to 2023). "According to a study by Wang and colleagues from 2010, ING4 down-regulation is closely linked to the initiation and progression of human lung cancer." (PMID 31390718, 2019). "Here it is found that ING4 induced PD‐L1 autophagic degradation and inhibites non‐small cell lung cancer (NSCLC) immune escape by increasing T cell activity." (PMID 37870169, 2023). "In this study, BSF modified with low-molecular-weight PEI is used to encapsulate ING4 and IL-24 double gene coexpression plasmids to establish a high-efficiency and low-toxicity gene delivery carrier against lung cancer cells." (PMID 34685354, 2021). "ING4-expressing recombinant adenoviral vectors in human pancreatic and lung carcinoma cell lines alter the cell cycle with a reduction in S-phase and arrest of the G2/M phase." (PMID 30643005, 2019). "As a conclusion, ING4 acts as a tumor suppressor in lung cancer, and its inhibition leads to initiation and progression of the disease." (PMID 31390718, 2019). "In conclusion, this study by Xie and colleagues provides a valid overview of the various anti-carcinogenic anchor points of ING4 in lung cancer." (PMID 31390718, 2019). "In the mouse xenograft model, Ad-ING4-IL-24 treatment resulted in synergistic inhibition of A549 lung carcinoma subcutaneous tumor growth." (PMID 31390718, 2019). "Therefore, a gene delivery system, constructed with the low-molecular-weight PEI-modified silk fibroin protein and the ING4-IL-24 double gene coexpression plasmid has potential applications in gene therapy for lung cancer." (PMID 34685354, 2021). "The results of this paper show that CBSF, as a gene carrier, can encapsulate the ING4-IL-24 double gene and further effectively transfect lung cancer A549 cells and significantly inhibit the proliferation of A549 cells, but has no obvious toxicity to normal WI-38 cells." (PMID 34685354, 2021). "Furthermore, 38.7% of A549 lung cancer cells went into apoptosis upon ING4 transfection, as compared to the control A549 cells cultured in the absence of ING4, where the apoptosis rate did not exceed 2%." (PMID 31390718, 2019). "In the future, ING4 might serve as a prognostic biomarker in several lung cancer subtypes." (PMID 31390718, 2019). "A549 lung cancer cells were transfected with recombinant adenoviral vectors (Ad-green fluorescent protein (GFP), Ad-ING4-GFP, Ad-DGFP (D means excision), and Ad-ING4-DGFP)." (PMID 31390718, 2019). "Adenovirus-mediated co-expression of ING4 and IL-24 in NSCLC cells resulted in growth suppression and apoptosis in the lung cancer cell lines in vitro." (PMID 31390718, 2019). "Notably, there is very limited data available on the effect of ING3 in lung cancer, whereas the function of ING1, ING2, ING4, and ING5 has been investigated in lung cancer in more detail." (PMID 31390718, 2019).
colon carcinoma (6 papers, 2012 to 2023). "Liprin-α1 interacts with ING4 (inhibitor of growth 4), and positively regulates cell migration in RKO colon carcinoma cells in ING4-dependent manner." (PMID 34654889, 2021).
lung adenocarcinoma (6 papers, 2013 to 2023). A carcinoma that arises from the lung and is characterized by the presence of malignant glandular epithelial cells. "For that purpose, ING4 cDNA was transduced into the lung adenocarcinoma cells, and FCM analysis, TUNEL assay and electron microscopy were performed." (PMID 31390718, 2019). "Li and colleagues have conducted a cell culture study examining A549 lung adenocarcinoma cells with respect to ING4." (PMID 31390718, 2019). "The aim of this study is to investigate the inhibitory effect and anti-cancer mechanism of adenovirus-mediated ING4 gene on SPC-A1 human lung adenocarcinoma in nude mice." (PMID 24581166, 2014). "ING4 gene elicited a remarkable growth inhibitory effect on human lung adenocarcinoma xenografts in nude mice." (PMID 24581166, 2014). "Our findings demonstrated that miR-650 confers the docetaxel chemoresistance of lung adenocarcinoma cells via regulating Bcl-2/Bax expression by targeting ING4." (PMID 23991130, 2013). "ING4 is proven to be a modulator of docetaxel (DTX) and paclitaxel sensitivity to overcome drug resistance in human lung adenocarcinoma and colorectal cancer." (PMID 30643005, 2019). "Bioinformatic analysis shows that ING4 expression has a positive correlation with CD8+ T cell infiltration and activated CD8+ T cells in lung squamous cell carcinoma (LUSC) but not in lung adenocarcinoma (LUAD)." (PMID 37870169, 2023).